HMGB1 (high mobility group box 1)
Diseases named in the same sentence as HMGB1 in open-access papers (continued):
Sharing a sentence is not in itself a finding about the gene and the disease.
glaucoma (11 papers, 2012 to 2025). Increased pressure in the eyeball due to obstruction of the outflow of aqueous humor. "HMGB1 concentrations were significantly higher in the aqueous humor of primary open-angle glaucoma patients, whereas in rodents, HMGB1 was linked to glaucoma induced by elevated IOP." (PMID 35269741, 2022). "In rats, HMGB1 has been linked to glaucoma induced by elevated intraocular pressure." (PMID 30473885, 2018). "In a rat model of glaucoma, treatment with an anti-HMGB1 antibody improved the survival of retinal ganglion cell." (PMID 40303351, 2025). "High expression of high-mobility group box protein 1 (HMGB1) plays a detrimental role in inflammatory processes and is elevated in the retinas of glaucoma patients." (PMID 35456925, 2022). "In glaucoma, BDNF has already been shown to modulate neuroprotection, highlighting the potential of HMGB1 as a target for possible intervention in glaucoma." (PMID 34943212, 2021). "A key molecule that also interacts directly with the complement system and was up-regulated in glaucoma patients is the high mobility group protein B1 (HMGB1)." (PMID 34943212, 2021). "This study aims to explore the role of high-mobility group box 1 (HMGB1) in an acute glaucoma mouse model." (PMID 26224068, 2015). "The results of our proteomic and Western blot analysis revealed that HMGB1 expression is up-regulated in the retina exposed to elevated IOP in the inherited glaucoma rat model." (PMID 22792152, 2012). "Therefore, the present study aimed to evaluate the neuroprotective effects of the intravitreal injection of an anti-HMGB1 antibody in a glaucoma animal model." (PMID 35456925, 2022). "Therefore, this study aimed to investigate the effects of the intravitreal injection of an anti-HMGB1 monoclonal antibody (anti-HMGB1 Ab) in an experimental animal model of glaucoma." (PMID 35456925, 2022). "It has been described several times that glaucoma also has an autoimmune component that may contribute to disease progression, again showing that modulation of HMGB1 protein may be a promising approach for glaucoma disease therapy." (PMID 34943212, 2021). "The HMGB1/NLRP3 axis is crucial in the progression of ocular diseases, particularly in retinal damage and glaucoma." (PMID 40688353, 2025). "The increased release of HMGB1 regulates NLRP3 activation through an NF-κB-dependent mechanism, contributing to retinal damage and potentially progressing to glaucoma." (PMID 40688353, 2025). "In conclusion, this study showed that an anti-HMGB1 Ab improved the survival of RGCs and axons in a chronic elevated-IOP glaucoma animal model compared with a control." (PMID 35456925, 2022). "Further investigations are required to elucidate the potential neuroprotective mechanisms of HMGB1, calmodulin, HSP70 and carbonic anhydrase II in glaucoma and develop eye drops that exert neuroprotection through direct pharmacological effect." (PMID 22792152, 2012). "Further investigations are required to elucidate the potential neuroprotective mechanisms signaled through changes of HMGB1, calmodulin, HSP70 and carbonic anhydrase II expression in glaucoma." (PMID 22792152, 2012). "The effect of an anti-HMGB1 Ab in a long-term glaucoma model with chronic IOP elevation has not yet been investigated." (PMID 35456925, 2022). "High-mobility group box 1 (HMGB1) protein is an abundant protein that has been shown to be involved in the pathogenesis of several inflammatory diseases, including elevated IOP-induced of the inherited glaucoma rat model." (PMID 26224068, 2015). "In addition to the IOP induced alterations of the retinal proteome in the inherited glaucoma rat model, we found a drug-specific and IOP-independent regulation of HMGB1 and calmodulin." (PMID 22792152, 2012). "Furthermore, in a rat glaucoma animal model, travoprost but not dorzolamide eye drops decreased HMGB1 expression in the retina, despite a successful decrease in IOP with both eyedrops." (PMID 35456925, 2022).
glaucoma (continued). "This indicates that HMGB1 might play a critical role in inflammatory responses in glaucoma disease, which is independent of the elevated IOP." (PMID 35456925, 2022).
head and neck squamous cell carcinoma (11 papers, 2016 to 2025). A squamous cell carcinoma that arises from any of the following anatomic sites: lip and oral cavity, nasal cavity, paranasal sinuses, pharynx, larynx, and salivary glands. "A recent study reported that the serum concentration of HMGB1 increased after NIR-PIT in head and neck squamous cell carcinoma patients." (PMID 41362788, 2025). "In our longitudinal pilot study, High Mobility Group Box 1 protein (HMGB1) was found to be a promising biomarker to monitor tumor response in definitive radiochemotherapy for head and neck squamous cell carcinoma." (PMID 34671818, 2022). "PDT was also reported to induce a further increase in the number of regulatory T cells and NK cells and upregulate HMGB1 expression in the peripheral blood of patients with head and neck squamous cell carcinoma (HNSCC)." (PMID 32528867, 2020). "Thus, we investigated the levels of HMGB1 in plasma of patients with head and neck squamous cell carcinoma (HNSCC) during the course of radiochemotherapy and follow-up in correlation with oncologic outcome and clinical confounders." (PMID 34671818, 2022). "Another interesting study involved Temoporfin-PDT in head and neck squamous cell carcinoma (HNSCC), where increased serum levels of IL-6 were detected with a peak at 24 h, and HMGB1 with a peak at one week after treatment, further supporting PDT as a potent inducer of acute inflammation." (PMID 31991650, 2020). "On the other hand, HMGB1 levels were found to increase following chemoradiation only in patients with locally advanced head and neck squamous cell carcinoma who did not relapse, as opposed to the patients who relapsed." (PMID 35903697, 2022). "In the present study, we investigated the expression and significance of high mobility group box 1 (HMGB1), HMG nucleosome-binding protein 1 (HMGN1), the receptor programmed cell death 1 (PD-1) and its ligand programmed cell death ligand 1 (PD-L1) in head and neck squamous cell carcinoma (HNSCC)." (PMID 30619746, 2018).
malaria (11 papers, 2009 to 2024). Malaria is a serious and sometimes fatal disease caused by a parasite that commonly infects a certain type of mosquito which feeds on humans. "The genome of the malaria parasite encodes four HMGB proteins—HMGB1, HMGB2, HMGB3, and HMGB4 that are conserved across the Plasmodium species." (PMID 39341498, 2024). "The parasite HMGB1 can regulate the expression of Plasmodium interspersed repeat (pir) multigene families that are associated with host-immune evasion and malaria pathogenesis." (PMID 39341498, 2024). "Moreover, in a mouse model of malaria-associated acute lung injury, both plasma and lung tissue showed high levels of HMGB1." (PMID 37511276, 2023). "It was hypothesized that malaria-induced release of HMGB1 from immune effector cells could be involved in the propagation of inflammation leading to malaria-associated immunopathology." (PMID 23506269, 2013). "Sera from patients with severe and uncomplicated malaria have significantly higher circulating HMGB1 levels compared with healthy controls." (PMID 34431854, 2021). "HMGB-1 elevation was reported an as informative prognostic marker for disease severity in human severe malaria." (PMID 27515948, 2016). "The utility of HMGB1 to distinguish severe malaria (SM; n = 70) from uncomplicated malaria (UM; n = 33) patients and fatal (n = 21) versus non-fatal (n = 82) malaria, at presentation, was examined." (PMID 23506269, 2013). "In this study, extracellular HMGB1 was quantified in plasma from 103 febrile Ugandan children with either uncomplicated malaria (UM) or SM by ELISA." (PMID 23506269, 2013). "This study supports further investigation into the potential use of HMGB1 as a biomarker to assess disease severity and prognosis in paediatric malaria." (PMID 23506269, 2013). "Additional prospective, multicentre studies of SM in areas of varying malaria transmission are required to validate the clinical utility of HMGB1." (PMID 23506269, 2013). "Such insights would help us to understand the virulence and immune evasion mechanisms of malaria parasites, and explore the possibility of developing a genetically attenuated blood-stage vaccine for malaria if HMGB1 deletion can lead to self-clearance and protection for human parasites." (PMID 39341498, 2024). "Parasitised erythrocytes induce HMGB1 release from human peripheral blood mononuclear cells in vitro and the neutralisation with antibodies directed against HMGB1 reduces mortality in a murine model of severe malaria." (PMID 34431854, 2021). "In human malaria, endogenous HMGB1 serum levels are significantly higher in patients with severe disease compared to uncomplicated cases, suggesting that HMGB1 might also be involved in the development of immunopathology." (PMID 26441984, 2015). "The potential role of HMGB1 in the pathogenesis of infectious syndromes associated with pronounced systemic inflammation suggests that HMGB1 may contribute to disease severity and outcome in malaria." (PMID 23506269, 2013). "falciparum co-culture approach, P. falciparum-PEs were shown in this study to induce HMGB1 release from human PBMCs, which may account for elevated plasma/serum levels observed in malaria patients." (PMID 23506269, 2013). "The adhering elements can set up local foci of inflammation, generating more inflammatory cytokines including inflammatory cascades initiated by HMGB1 released from the adhering activated platelets which may limit progression from uncomplicated malaria to severe complication." (PMID 36852070, 2023). "Moreover, HMGB1 levels were predictive of malarial disease severity and clinical outcome, suggesting that quantification of extracellular HMGB1 may be a useful prognostic marker of severe and fatal malaria." (PMID 23506269, 2013). "Antibody-mediated neutralization of HMGB1 in the experimental murine model of severe malaria failed to reduce mortality." (PMID 23506269, 2013).
malaria (continued). "In these 13 children, CRP, s-TREM-1, CD163 and HMGB1 were higher than in those negative for malaria parasites, but these differences were not significant." (PMID 19675669, 2009). "However, based on the results of this study in a mouse model of SM, HMGB1 neutralization using anti-HMGB1 2G7 mAb does not appear to be a viable therapeutic strategy to improve clinical outcome in this model of severe malaria." (PMID 23506269, 2013). "Some, but not all, studies suggest that HMGB1 does not have direct cytokine activity but instead functions as a complex with TLR ligands (e g, LPS) to enhance or promote their effects, a function that may not be relevant for severe malaria pathology caused by malaria toxins or by-products." (PMID 23506269, 2013).
nasal polyps (11 papers, 2015 to 2025). "The study enrolled 45 patients and included an in vitro investigation using cultured dispersed nasal polyp cells (DNPCs) to assess the effects of TLR9 activation on HMGB1 and immune response." (PMID 40807013, 2025). "A study from 2019 explored the role of HMGB1 in driving EMT in eosinophilic chronic rhinosinusitis with nasal polyps (ECRSwNP) whilst also highlighting the therapeutic potential of peroxisome proliferator-activated receptor-γ (PPAR-γ) agonists." (PMID 40807013, 2025). "The results showed that LPS affects the translocation and release of HMGB1, suggesting its potential involvement in chronic rhinosinusitis with nasal polyps mediated by inflammatory factors." (PMID 37828579, 2023). "Here, we study RAGE and HMGB1 expression in chronic, recalcitrant rhinosinusitis with nasal polyps (CRSwNP) to determine its potential clinical significance, i.e., disease recurrence and severity." (PMID 25503556, 2015). "Notwithstanding this evidence, and the fact that RAGE and HMGB1 have been proposed as a novel therapeutic target for infectious and inflammatory disorders, no data have been published concerning the expression and function of RAGE and HMGB1 in recalcitrant nasal polyposis." (PMID 25503556, 2015). "In preliminary experiments, immunohistochemistry (IHC) for HMGB1 was performed using a variety of normal human tissues rich in inflammatory infiltrates such as oral mucosa, intestine, or nasal polyps of patients with chronic rhinosinusitis and also tumor issues such as HNSCC." (PMID 25385222, 2015). "HMGB1 closely contributes to chronic rhinosinusitis with or without nasal polyps." (PMID 34445093, 2021). "Furthermore, the upregulation of SIRT6 gene expression in nasal mucosal epithelial cells can inhibit the migration of high mobility group protein 1 (HMGB1) induced by lipopolysaccharide (LPS), suggesting that SIRT6 may inhibit the development of nasal polyps by altering inflammatory processes." (PMID 35620467, 2022).
rectal cancer (11 papers, 2015 to 2025). A primary or metastatic malignant neoplasm that affects the rectum. "For instance, in the treatment of rectal cancer, the increase in HMGB1 was associated both with poorer and with better responses to chemoradiotherapy." (PMID 36015189, 2022). "In conclusion, using immunohistochemistry, this study demonstrated the association of HMGB1 expression in human rectal cancer tissue exposed to CRT with tumor invasiveness and resistance to therapy." (PMID 25622595, 2015). "Further large-scale prospective studies with long-term follow-up periods, evaluating samples obtained pre- and post-CRT, are needed to determine the potential role of HMGB1 as a prognostic factor for CRT in rectal cancer." (PMID 25622595, 2015). "In this study, we aimed to investigate the correlation of HMGB1 expression and resistance of rectal cancer patients to chemoradiotherapy (CRT) prior to curative operation." (PMID 25622595, 2015). "In our series, HMGB1 expression significantly correlated with the histological type of tumor, lymphatic invasion, and venous invasion in rectal cancer." (PMID 25622595, 2015). "Researchers have reported that HMGB1 may regulate the reactivity of rectal cancer cells to preoperative chemoradiotherapy." (PMID 35354479, 2022). "HMGB1 expression may be one of the key factors regulating the response of rectal cancer to preoperative CRT in terms of tumor invasiveness and resistance to therapy." (PMID 25622595, 2015). "This may imply that rectal cancers with high HMGB1 expression have higher malignancy potential, acquiring resistance to CRT." (PMID 25622595, 2015). "Thus, targeting of HMGB1 may be a promising approach for the development of novel therapeutic strategies for rectal cancer." (PMID 25622595, 2015). "Another study in rectal cancer found that HMGB1 knockdown by RNAi activated caspase-3 and PARP, downregulated Bcl-2 expression and eventually induced apoptosis in rectal cancer cells." (PMID 30157958, 2018). "In this study, we focused on the HMGB1 staining pattern in the nuclear compartment, but not the cytoplasm, of rectal cancer cells, and evaluated its possible role in tumor progression and resistance to treatment." (PMID 25622595, 2015). "Furthermore, high HMGB1 expression corelated with poorer response to neoadjuvant chemoradiation in rectal cancer patients, albeit in a small cohort who failed to achieve a complete response and there was no assessment of expression pre- and post-treatment." (PMID 38353760, 2024).
Cirrhosis (10 papers, 2014 to 2025). A chronic disorder of the liver in which liver tissue becomes scarred and is partially replaced by regenerative nodules and fibrotic tissue resulting in loss of liver function. "In general, these results were less clear, as levels of HMGB‐1 were unexpectedly higher in patients with compensated cirrhosis, than patients with decompensated cirrhosis pre‐TIPS." (PMID 39533838, 2025). "We used GeoMx spatial analysis on a cirrhosis mouse model created using CCl4 and treated with HMGB1 peptide synthesized from Box A of HMGB1." (PMID 40503100, 2025). "To assess the temporal effects of HMGB1 on the liver in a CCl4-induced cirrhosis mouse model, we used GeoMx spatial analysis." (PMID 40503100, 2025). "We have previously shown that HMGB1 peptide reduces liver injury and improves fibrosis in a cirrhosis model induced by carbon tetrachloride (CCl4)." (PMID 40503100, 2025). "Overall, in this study, we demonstrated the therapeutic effects of HMGB1 peptide in a mouse model of cirrhosis." (PMID 34565478, 2021). "In our previous study, the upregulation of HMGB1 was found to be strongly correlated with cirrhosis in HCC." (PMID 34497155, 2021). "Overall, we established a new concept for cell-free therapy using HMGB1 peptide for cirrhosis through the induction of anti-inflammatory macrophages." (PMID 34565478, 2021). "As determined in the gene expression profiles following WISP2 overexpression in HCC cells, HMGB1 was significantly upregulated, and this upregulation was found to be strongly correlated with cirrhosis in our previous study." (PMID 34497155, 2021). "In this study, we analyzed the therapeutic effects of a peptide synthesized from box A of HMGB1 (called HMGB1 peptide) on macrophage function and liver damage in a carbon tetrachloride (CCl4)-induced cirrhosis mouse model." (PMID 34565478, 2021). "•HMGB1 peptide treatment reduces αSMA-positive cells from week two in cirrhosis model." (PMID 40503100, 2025). "However, we believe that we have identified a mechanism by which the HMGB1 peptide can reduce liver injury and ameliorate fibrosis in both cirrhosis and MASH liver models through multiple effects." (PMID 40503100, 2025). "Indeed, in our mouse cirrhosis model, we confirmed that HMGB1 peptide had similar effects as macrophage, MSC, and MSC and macrophage combination therapies." (PMID 34565478, 2021). "Secreted HMGB1 may also have a role in cirrhosis, a common comorbidity in patients with HCV." (PMID 37298365, 2023). "Since serum HMGB1 and IL-6 can accumulate in urine during AKI-associated inflammatory processes, both could be useful in the differential diagnosis of the causes of AKI in cirrhosis patients—especially between parenchymal renal disease and functional AKI—similar to other urinary biomarkers." (PMID 33061824, 2020). "The IHC analysis demonstrated a robust increase in HMGB1 expression in patients with acute ASH superimposed on ALD and cirrhosis compared with healthy specimens (top)." (PMID 24928512, 2014). "Therefore, it is possible that the anti‐inflammatory redox state is more prevalent in patients with compensated cirrhosis, so that recompensation by TIPS increases rather the anti‐inflammatory isoform of HMGB‐1." (PMID 39533838, 2025). "However, during follow‐up, HMGB‐1 levels increased after TIPS, reaching levels comparable to the ones of patients with compensated cirrhosis." (PMID 39533838, 2025). "Overall, the peritumoral expression of HMGB1 was lower in the patients with HBV-negative HCC than in the patients with HBV-positive HCC (p = 0.004), which might be attributed to the background of cirrhosis." (PMID 27836008, 2016).